SOD2 (superoxide dismutase 2)
Diseases named in the same sentence as SOD2 in open-access papers (continued):
Sharing a sentence is not in itself a finding about the gene and the disease.
tumor (396 papers, 1996 to 2026). "For example, using mitochondrial antioxidants or other methods to regulate SOD2 function can inhibit tumor-associated inflammatory responses and reduce the tumor-promoting effect of inflammation." (PMID 40568576, 2025). "According to a different study, SOD2 is essential for the tumor-initiating characteristics linked to temozolomide resistance." (PMID 40867576, 2025). "Conversely, SOD2 is often downregulated in cancer cells, and its expression has been linked to tumour suppression." (PMID 38227157, 2024). "CRT-targeting L-ASNases specifically bound to ecto-CRT on tumor cells treated with IR and depleted Asn to enhance ROS production, which was associated with decreased expression of SOD2." (PMID 38323311, 2024). "SOD2 is a putative tumor-suppressor gene, deficiency of which is linked to proliferative diseases including PAH and cancers." (PMID 37087509, 2023). "A drug able to kill tumor cells in the metastatic setting would most likely cause an increase in the levels of circulating SOD2 as long as there is tumor cell death." (PMID 36010852, 2022). "We reasoned that being so robust to proteolysis and very abundant intracellularly, tumor cell death would cause a large increase in the levels of SOD2 in the supernatants of tumor cells treated with cytotoxic therapy." (PMID 36010852, 2022). "Activation of PPARD has also been associated with the increased expression of both SOD1 and SOD2, which are linked with tumor progression and migration in AFG1-induced LA." (PMID 35342393, 2022). "SOD2 expression increases cellular oxidant/antioxidant ratios, which are directly associated with tumor progression, angiogenesis and migration, and invasion." (PMID 35164076, 2022). "SOD-2 as either a tumor suppressor or promoter is intimately linked to its function as a regulator of mitochondrial oxidants." (PMID 35368886, 2022). "H2O2 increase due to SOD2 overexpression has been linked to differentiation, anti-tumor therapy resistance, and metastasis in the prostate." (PMID 35204196, 2022). "Loss of SOD2 represents a phenotype of tumor initiation and, therefore, is indicative of the tumor suppressor role of SOD2, particularly due to its scavenging role for superoxide anion during the process of tumorigenesis." (PMID 36009568, 2022). "In vivo studies have provided evidence of the association between high SOD2 expression and more aggressive tumor phenotypes." (PMID 34062984, 2021). "The loss of SOD2 expression has been reported to occur early in tumor progression, allowing the propagation of aggressive tumors and metastasis following the increase in free radical production." (PMID 33383666, 2020). "In summary, the strategy of combining the SOD2 inhibitor with TMZ would benefit tumor treatment through an enhancement of TMZ susceptibility and a reduction in the number of TICs." (PMID 31629402, 2019). "Mutant SOD2 drives tumor progression and metastasis by loss mitochondrial anti-oxidative stress functions." (PMID 29872510, 2018). "SOD2 increases during tumor progression have largely been linked to stress response pathways that positively regulate SOD2 transcription, including Nuclear Factor, Erythroid 2 Like 2 (Nrf2) and NF-κB signaling." (PMID 29099803, 2017). "The function of SOD2 as either a tumor suppressor or promoter is intimately linked to its function as a regulator of mitochondrial oxidants, specifically O2•− and H2O2." (PMID 29099803, 2017). "Given that expression data from large-scale datasets, including TCGA, contain a mixture of cancer cells and tumor-associated cells, the role and regulation of SOD2 between tumor cells and the tumor microenvironment need to be further delineated." (PMID 29099803, 2017). "It should be noted that studies have also pointed to altered SOD2 expression within tumor-associated cells themselves." (PMID 29099803, 2017). "We also found that AFG1 induced chronic lung inflammatory responses associated with SOD-2 upregulation at the pre-tumor stage." (PMID 28801561, 2017).
tumor (continued). "Our results show that SOD2 expression has some value by increasing the risk of metastasis when the tumor depth was greater than 5 mm." (PMID 25745358, 2015). "In the present study we have analyzed by immunohistochemistry the association of SOD2 expression pattern with different tumor aggressiveness and progression variables in 125 primary SCC samples of the usual histological type." (PMID 25745358, 2015). "Aggressive tumor behavior has been previously associated with increased SOD2 expression, and seems to be mediated by the ensuing high H2O2 levels." (PMID 22859959, 2012). "Therapeutic targeting of SOD2 has been proposed to not only directly harm applicable tumor cells, but also to increase their susceptibility to ROS-inducing chemotherapeutic agents." (PMID 22859959, 2012). "As predicted, over-expression of mitochondrial SOD2 in cancer associated fibroblasts was indeed sufficient to inhibit tumor growth by nearly two-fold." (PMID 21605374, 2011). "Conversely, partial SOD2 deficiency in early-stage models of thyroid and pancreatic neoplasia leads to increased mitochondrial and nuclear DNA damage and accelerated tumorigenesis, supporting a tumor-suppressive role in precancerous stages." (PMID 40867898, 2025). "In addition, in mice with aggressive TC, overexpression of SOD2 reduced tumor proliferation and mortality rates, whereas its deficiency enhanced tumor growth." (PMID 40927570, 2025). "However, more recent studies revealed that low levels of SOD2 are an early event of tumors, and higher levels of SOD2 are associated with tumor progression and metastasis." (PMID 36672191, 2023). "It has been shown that the loss of antioxidants, such as GPX1, GPX3 or SOD2, could increase tumor progression in several mouse models." (PMID 37834426, 2023). "Although most of the studies are focused on the impact of Sod2 polymorphisms in tumor incidence and progression, emerging evidence points to its role on specific hallmarks of cancer progression such as hormone independence and metabolic spread in the prostate and breast." (PMID 35204196, 2022). "Altogether, these results support our finding of SOD2 as being a crucial factor that is associated with tumor-initiating cell features for enrichment of these HNC subsets, which in turn could contribute to multi-drug resistance." (PMID 34681918, 2021). "Viable tumor cells in lymph nodes upon neoadjuvant treatment (i.e., ypN+) were less likely present in carriers of the homozygous variant CC genotype of SOD2 rs4880 in comparison to the combined group of TT and TC (RR 0.56, 0.33–0.95, p = 0.02, recessive allele effect)." (PMID 34199885, 2021). "Generally, in the early stages of disease, the expression of SOD2 is low, indicating that SOD2 could be associated with the onset of tumor development." (PMID 34062984, 2021). "Cd exposure to rat R2C tumor LC cells at 10–160 μM for 24 h also causes mitochondrial damage and lowers Star expression level and then inhibits steroid secretion, possibly by increasing ROS levels and decreasing SOD2 activity." (PMID 32528534, 2020). "The markedly increased expression of SOD2 in metastatic anaplastic thyroid cancer may be causally related to cancer-related modifications of tumor cell metabolism." (PMID 29478325, 2019). "We next sought to determine whether the most consistently upregulated antioxidant enzyme, SOD2, could be counteracting oxidative stress associated with telomere uncapping, and enabling tumor cells to survive with high levels of ROS." (PMID 29695835, 2018). "Whether this represents an additional mechanism for SIRT3-mediated SOD2 activation in response to stress associated with tumor progression requires further investigation." (PMID 29099803, 2017). "Tumor-associated inflammatory microenvironment was also elicited, which may be related to SOD-2 upregulation and EMT in cancer cells." (PMID 28801561, 2017).
tumor (continued). "However, few studies have directly assessed the role of tumor-associated cells on tumor cell SOD2 expression (e.g., co-culture models)." (PMID 29099803, 2017). "Here, we describe some of the mechanisms that underlie SOD2 regulation in tumor cells." (PMID 29099803, 2017). "Thus, MDSCs responded by expressing high levels of detoxifying enzymes and ROS scavenger proteins such as P450R, heme oxigenase 2, and Sod2 that is elevated in tumor-associated macrophages and tumor cells." (PMID 25151659, 2014). "Therefore, SOD2 may reflect the intrinsic aggressive character of the tumor in addition to the predisposed resistance to chemotherapy." (PMID 30700285, 2019). "Overall, the role of NF-κB-dependent SOD2 expression is likely the primary mechanism for increased SOD2 expression in response to pro-survival cytokine stimulation and a mechanism for adaptations against cellular redox stress associated with tumor metastasis and the microenvironment." (PMID 29099803, 2017). "Elevated SOD1 and SOD2 levels often promote oncogenic signalling and tumour survival, whereas SOD3 exhibits context-dependent roles, balancing tumour suppression and progression." (PMID 41799710, 2026). "SOD2 is a mitochondrial antioxidant gene that can be upregulated by the UPRmt, and it exhibits both tumor-suppressive and tumor-promoting functions through scavenging superoxide and regulating hydrogen peroxide levels." (PMID 41154474, 2025). "Our study revealed that KYNU, which is secreted predominantly by M2 macrophages in EC tissues, regulates SOD2 in tumor cells." (PMID 40616124, 2025). "The opposing roles of certain antioxidant enzymes, such as Mn-SOD (SOD2), illustrate the same duality as ROS, acting as potential tumor suppressors during early carcinogenesis and as tumor promoters during metastasis." (PMID 40906205, 2025). "Nimbolide (NB) therapy of PDAC xenografts overexpressing SOD2 significantly reduced tumor development and metastasis." (PMID 40867576, 2025). "The lysate also impaired the antioxidant defense system of tumor cells, reducing the expression of phosphorylated Nrf2 and SOD2, both of which play key roles in maintaining redox homeostasis." (PMID 41300439, 2025). "The results showed that compared to the control group, the SOD-2 and HO-1 protein levels in the gastrocnemius muscle of the tumor-only group significantly decreased (p < 0.001)." (PMID 40136406, 2025). "PE supplementation, which was more potent than tryptone, significantly increased SOD2 and HO-1 protein expression in the gastrocnemius muscle of tumor-bearing mice (p < 0.05)." (PMID 40136406, 2025). "The traditional herbal formula Shashen-Maidong Decoction suppresses tumor growth under intermittent hypoxia by restoring mitochondrial SOD2 expression and downregulating IL-6/JAK2/STAT3 signaling, thereby linking oxidative and inflammatory responses." (PMID 40722961, 2025). "One main antioxidant enzyme is mitochondrial superoxide dismutase (SOD2) which has been shown to influence tumor initiation and metastatic progression in several cancer types." (PMID 41353397, 2025). "In contrast, SM-2 treatment down-regulated GDF15 expression in cocultured tumor cells, suppressed ROS levels, and reduced expression of Nrf2 and SOD2." (PMID 41035818, 2025). "APOM and SOD2 are involved in antioxidant defense, helping tumor cells survive in highly oxidative conditions." (PMID 40989695, 2025). "Our findings demonstrate for the first time that overexpression of SOD2 is critical in preventing the reactivation of QCCs by inducing apoptosis, suppressing the growth of recurrent tumours from quiescent PCa cells, and prolonging mice survival." (PMID 40520023, 2025). "In oral cancer, SOD2 acts both as a tumor suppressor and a tumor promoter, depending on the disease stage." (PMID 40422642, 2025).
tumor (continued). "Genetic variants of antioxidant enzymes, namely in SOD2, GPX1, and CAT, were already associated with the development of various neoplasms and treatment efficacy." (PMID 40565143, 2025). "Mitochondrial superoxide dismutase (SOD2), responsible for scavenging superoxide radicals in the mitochondria, also acts as a tumor suppressor by mediating the superoxide-to-peroxide ratio." (PMID 40429796, 2025). "In conclusion, our findings highlight the role of SOD2 in tumor progression and metabolic adaptation." (PMID 41353397, 2025). "The average times required to reach tumor volumes of 50, 100 and 200 mm3 were substantially prolonged in the SOD2-overexpressing group." (PMID 40520023, 2025). "For example, while cytosolic and mitochondrial superoxide dismutase (SOD1 and SOD2) were more abundant in tumor tissue (especially the mitochondrial isoform SOD2), SOD3, the excreted isoform, was significantly more abundant in healthy tissue." (PMID 40461450, 2025). "Caveolin-1 and mitochondrial SOD2 (MnSOD) function as tumor suppressors in the stromal microenvironment." (PMID 37469162, 2024). "For example, SIRT3 can promote tumor growth by enhancing the deacetylation and thus activity of SHMT2, but it can also exert anti-tumor effects by increasing SOD2 activity and reducing ROS production." (PMID 39763669, 2024). "The expression of superoxide dismutase (P04179), which is directly related to tumor progression, invasion and angiogenesis and is synthesized by the SOD2 gene, is higher in premenopausal EC patients than in postmenopausal EC patients (p < 0.001)." (PMID 38894711, 2024). "In general, over-expressed GSH and manganese superoxide dismutase(SOD2) play important roles in tumor cells’ resistance to ROSdamage." (PMID 38422393, 2024). "Previous data suggested that circRANGAP1 and SOD2 functions as oncogenes, while miR-512-5p acts as a tumor suppressor." (PMID 38082189, 2024). "Tumor cells can produce large amounts of ROS during glycolysis, and SOD2 can break down ROS into H2O2 and oxygen." (PMID 39871949, 2024). "In patient samples, SOD2 protein levels were significantly increased in tumor (Gleason 3–9) compared to hyperplasic or control tissues and correlated with prostate cancer patient Gleason scores." (PMID 39000269, 2024). "Control sample and low-grade tumor (Gleason 5) had much lower SOD2 levels than medium-grade tumors (Gleason 7), and high-grade tumors (Gleason 8) had even higher SOD2 protein levels." (PMID 39000269, 2024). "A second study in 1982 used the maxillary sinus VX2 model to characterize the expression levels of superoxide dismutase 2 (SOD2) in tumor cells and in various other organs of tumor-bearing rabbits." (PMID 39599834, 2024). "Overexpression of SOD2 induces a radioactivity-sensitizing effect on existing tumor cells and a protecting effect on normal cells." (PMID 38732562, 2024). "For instance, myoCAFs and CXCL12+ iCAFs were predominantly abundant in four tumor groups, and SOD2+ iCAFs were exclusively found in the UCCC group." (PMID 39112478, 2024). "Under basal conditions, the overexpression of wild-type SOD2 suppressed soft agar colony formation or xenograft tumor growth in androgen-independent PC3 and Du145 cells, as well as in androgen-responsive M12 cells." (PMID 39000269, 2024). "Concurrently, the 17-DMAG-loaded DE532 Ex demonstrated the lowest suppression of antioxidant enzymes, such as superoxide dismutase 2 and catalase, within tumor tissues." (PMID 39201449, 2024). "For instance, in CRC, immunochemistry analysis has revealed a higher expression of SOD2 protein in tumor tissue than in the normal tissue adjacent." (PMID 37533102, 2023). "NB treatment was highly effective in inhibiting the aggressive tumor growth of SOD2-overexpressing PDAC xenografts." (PMID 37891871, 2023).
tumor (continued). "The function of SOD2 as a tumor suppressor or promoter was closely related to its function as a mitochondrial oxidant regulator, which played a cytoprotective role by scavenging harmful oxygen free radicals in the main cell metabolic centers." (PMID 37759978, 2023). "Oxidative stress markers and SOD2 also increased in response to treatment with rucaparib within the tumor cells of the treated animals." (PMID 36768904, 2023). "In human cells, pro- and anti-tumorigenic roles of Sod2 have been identified, which appear to be determined by the stage of cancer progression, the type of cancer, and the tumor environment." (PMID 37638880, 2023). "Previous data have revealed that a circular RNA derived from the superoxide dismutase 2 mitochondrial (SOD2) gene (circ-SOD2) is overexpressed in HCC tumor tissues compared to adjacent normal liver tissues." (PMID 37111734, 2023). "SOD2 is a key antioxidant, and it is localized in mitochondria and is found to act as potential tumor suppressor gene in carcinogenesis." (PMID 36809279, 2023). "Mechanically, the activated AKT1 phosphorylates and inhibits SOD2 in mitochondria, thereby promoting mitochondrial ROS accumulation and subsequent cell death in confined tumor cells." (PMID 37296072, 2023). "We also checked the impact of primary tumour size, the status of lymph nodes metastasis and distant metastasis, as well as the grading of histological malignancy on the level of methylation of SOD2 and NOS2 promoter regions." (PMID 37660159, 2023). "The proliferative marker pAkt displayed decreased expression with the NB treatment in SOD2-overexpressing tumor tissues." (PMID 37891871, 2023). "Both SOD1 and SOD2 protect against spontaneous tumorigenesis, and although they have been described as tumor suppressors, they can also be upregulated during tumorigenesis." (PMID 37107276, 2023). "Collectively, these results indicate that IGFBP1 supports the survival of confined cells and enhances confined migration of tumor cells and therefore promotes tumor metastasis by inhibiting SOD2 S27 phosphorylation." (PMID 37296072, 2023). "We observed that NB suppressed SOD2 to reduce tumor growth by targeting cell proliferation, EMT, apoptosis, and PI3K/Akt signaling in SOD2-overexpressing PDAC xenograft tumors." (PMID 37891871, 2023). "Oxidative stress and SOD2 also increased in response to treatment with rucaparib within the tumor cells of the treated mice." (PMID 36768904, 2023). "Meanwhile, mice with a reduced expression of SOD2, either alone or in combination with a loss of GPX1, showed increased DNA damage and tumor incidence." (PMID 37107276, 2023). "Our study identified a new phosphorylation of SOD2 at S27, which is removed in tumor cells during confined migration, thereby activating SOD2." (PMID 37296072, 2023). "For instance, increased SOD2 expression has often been observed in tumor tissues and is frequently correlated with tumor stage and metastasis activity." (PMID 36552527, 2022). "As an antioxidant factor, a high expression of SOD2 can enhance the ability of tumor cells to clear reactive oxygen species and inhibit malignant tumor growth." (PMID 36142828, 2022). "The initial in vitro validation studies prove that extracellular levels of SOD2 in cell lines correlate with the tumor cell death induced by chemotherapy." (PMID 36010852, 2022). "SOD2 is a protein overexpressed in cancer, probably because it alleviates the molecular damage induced by the increase in oxidative stress that tumor cells experience." (PMID 36010852, 2022). "The results showed that circulating levels of SOD2 increased when patients responded to the treatment according to the tumor shrinkage during neoadjuvant chemotherapy." (PMID 36010852, 2022). "In contrasts, a high tumor content of the mitochondrial enzymes involved in scavenging superoxide radical (SOD2) and hydrogen peroxide (PRX3), predicted poor OS and DFS for the patients." (PMID 35534478, 2022).